HEIH (hepatocellular carcinoma up-regulated EZH2-associated long non-coding RNA)
Synonyms: LINC-HEIH; lncRNA-HEIH; LINC00848; HCCAT2
Gene: Long non-coding RNA gene on chromosome 5 (180,824,604 to 180,861,858, reverse strand). Ensembl gene ENSG00000278970.
Diseases named in the same sentence as HEIH in open-access papers:
HEIH is named in the same sentence as 29 diseases in open-access papers, as found by Europe PMC text mining. Sharing a sentence is not in itself a finding about the gene and the disease. The quoted sentences say what the papers report.
hepatocellular carcinoma (19 papers, 2014 to 2025). A malignant tumor that arises from hepatocytes. "Studies have pinpointed specific lncRNAs, such as HULC (Highly Upregulated in Liver Cancer) and HEIH (hepatocellular carcinoma UpRegulated EZH2-Associated Long Noncoding RNA), with elevated expression in HCC patients." (PMID 38203767, 2024). "GC patients with higher expression levels of HEIH (Hepatocellular Carcinoma Upregulated EZH2-Associated Long Noncoding RNA) exhibited a poorer prognosis in comparison to those with lower HEIH expression." (PMID 38294554, 2024). "The Hepatocellular Carcinoma Upregulated EZH2-Associated Long Non-Coding RNA (HEIH) is a recently identified intergenic lncRNA localized on chromosomal region 5q35.3." (PMID 36290744, 2022). "High Expression in Hepatocellular carcinoma (lnc-HEIH) promotes tumor growth by directly associating with enhancer of zeste homologue 2 (EZH2) to suppress its enzymatic activity." (PMID 36551958, 2022). "HEIH was initially characterized as an oncogenic lncRNA in HBV-related hepatocellular carcinoma for its ability to inhibit cell differentiation." (PMID 36290744, 2022). "Numerous reports have revealed that HEIH play a central part in all kinds of tumors, including hepatocellular carcinoma, cholangiocarcinoma and esophageal cancer." (PMID 36118855, 2022). "HEIH was highly expressed in tumor tissue, and HEIH reduction significantly reduced Huh7 and Hep3B hepatoma cell viability, migration, and invasion and induced apoptosis." (PMID 34123955, 2021). "One example of such oncogenic lncRNAs is HEIH transcript which is overexpressed in hepatitis B virus‐related hepatocellular carcinoma." (PMID 32729661, 2020). "Furthermore, the extent of HEIH gene expression in primary hepatocellular carcinoma is a powerful indicator of treatment outcomes." (PMID 32729661, 2020). "Finally, ENST00000545462 (also described as HEIH, a prognostic factor in hepatocellular carcinoma), has pronounced staining in the nuclear periphery, as well as within the nucleolus and diffuse staining in the cytoplasm." (PMID 27090285, 2016). "HEIH (hepatocellular carcinoma upregulated EZH2-associated long noncoding RNA), located in chromosome 5q35, is a 1.7 kb transcript that is overexpressed in HCC patients and negatively correlates with cumulative survival." (PMID 38203767, 2024). "The lncRNAs H19, HULC, HEIH, MVIH are highly upregulated in hepatocellular cancer and are valuable biomarkers for the same." (PMID 26082843, 2015).
melanoma (8 papers, 2017 to 2023). A malignant, usually aggressive tumor composed of atypical, neoplastic melanocytes. "High levels of HEIH are associated with advanced clinical stages and might predict poor clinical outcomes in melanoma patients." (PMID 34638331, 2021). "It has been reported that HEIH knockdown inhibits proliferation, migration and invasion of melanoma cell lines." (PMID 37325482, 2023). "A previous report showed that lncRNA HEIH also has oncogenic roles in melanoma via repressing miR-200b/a/429, which is consistent with the action mechanisms of ILF3-AS1 in melanoma." (PMID 28935763, 2017). "Elevated expression of HEIH has correlated with advanced clinical stages of the disease and may serve as a predictor of poor outcome in melanoma patients." (PMID 37325482, 2023). "Therefore, we next investigated whether the oncogenic role of ILF3-AS1 is redundant with that of HEIH in melanoma." (PMID 28935763, 2017). "Other lncRNAs that contribute to gene repression in melanoma through direct interaction with EZH2 are CASC5, FALEC, HEIH, LNMAT1 and PVT1." (PMID 34638331, 2021).
colorectal cancer (4 papers, 2020 to 2022). A primary or metastatic malignant neoplasm that affects the colon or rectum. "In colorectal cancer, HEIH promotes the development of colorectal cancer by regulating the miR-939/Bcl-XL axis." (PMID 36246567, 2022). "For example, lncRNA HEIH promotes tumorigenesis in colorectal cancer via counteracting the effect of miR-939 on the transcriptional repression of Bcl-xL." (PMID 31992960, 2020).
liver cancer (4 papers, 2020 to 2024). An epithelial or non-epithelial malignant neoplasm that arises from the liver. "Silencing of lncRNA HEIH inhibits liver cancer cell growth and metastasis through miR-199a-3p/mTOR axis." (PMID 33899079, 2021).
endometrial cancer (3 papers, 2020 to 2023). Primary or metastatic malignant neoplasm involving the endometrium (mucous membrane that lines the endometrial cavity). "In terms of treatment, LncRNA HEIH can enhance the tolerance of endometrial cancer cells to paclitaxel by activating the MAPK signaling pathway." (PMID 37124623, 2023). "Other studies have also found that lncRNA HEIH regulates paclitaxel-resistance, viability and proliferation of endometrial cancer cells through MAPK signaling pathway." (PMID 36466815, 2022).
gastric cancer (2 papers, 2020 to 2022). A primary or metastatic malignant neoplasm involving the stomach. "The results showed that HEIH expression was upregulated in gastric cancer tissues compared with adjacent tissues, and the difference was statistically significant." (PMID 36246567, 2022). "HEIH can promote malignant proliferation of gastric cancer cells and promote tumor proliferation and invasion in vitro." (PMID 36246567, 2022). "Our results suggest that HEIH can inhibit autophagy by regulating STAT3 in gastric cancer cell lines." (PMID 36246567, 2022). "The objective of this study was to determine the abnormal expression of HEIH in human gastric cancer and to investigate the relationship between HEIH differential expression and malignant degree of gastric cancer." (PMID 36246567, 2022). "It was suggested that HEIH upregulation was positively correlated with worse prognosis in gastric cancer." (PMID 36246567, 2022). "In order to investigate the clinical value of HEIH, qRT-PCR was used to confirm the high expression of HEIH in gastric cancer." (PMID 36246567, 2022). "In order to study the effect of HEIH on the biological function of gastric cancer cells, we downregulated and upregulated HEIH expression in gastric cancer cells." (PMID 36246567, 2022). "HEIH promotes gastric cancer development by inhibiting miR-4500." (PMID 36246567, 2022). "The results suggest that HEIH can regulate the malignant proliferation of gastric cancer cells." (PMID 36246567, 2022). "This study confirmed that HEIH is upregulated in gastric cancer tissues." (PMID 36246567, 2022). "In this study, HEIH can also promote glycolysis of gastric cancer cells by regulating STAT3." (PMID 36246567, 2022). "The results showed that HEIH was highly expressed in gastric cancer (P < 0.01)." (PMID 36246567, 2022). "HEIH may be a new candidate site for pathological diagnosis and molecular drug therapy for future clinical treatment of gastric cancer." (PMID 36246567, 2022). "It is suggested that abnormally high expression of HEIH may be one of the factors of poor prognosis in patients with gastric cancer." (PMID 36246567, 2022). "HEIH promotes malignant proliferation and development of gastric cancer cells." (PMID 36246567, 2022). "The correlation results of STAT3 and HEIH expression in gastric cancer tissue showed that STAT3 and HEIH showed coexpression positive correlation." (PMID 36246567, 2022). "Interference of HEIH expression in MGC-803 and BGC-823 cells reduced the proliferation and invasion of gastric cancer cells, and the results were statistically significant (P < 0.05)." (PMID 36246567, 2022). "Mechanism studies have shown that upregulated HEIH binds miR-4500 to affect autophagy and glycolysis through the STAT3 signaling pathway and promote the proliferation and migration of gastric cancer cells." (PMID 36246567, 2022). "qRT-PCR was used to analyze the expression of HEIH in 30 cases of gastric cancer and nontumor brain tissues." (PMID 36246567, 2022).
ovarian carcinoma (2 papers, 2021 to 2022). A malignant neoplasm originating from the surface ovarian epithelium. "Moreover, in ovarian cancer, HEIH facilitated cell progression and blocked cell senescence by regulating miR-3619-5p and CTTNBP2." (PMID 34760016, 2021).
bladder cancer (1 paper, 2021). "In this experiment, we found that HEIH was upregulated in bladder cancer cell lines (T24, 5637, HT-1197, TCCSUP, and SW780)." (PMID 34760016, 2021). "To investigate the function of HEIH in bladder cancer progression, we knocked down the expression of HEIH in T24 and SW780 cells." (PMID 34760016, 2021). "Besides this, we noticed that HEIH knockdown blocked cell proliferation, migration, and invasion but facilitated cell apoptosis in bladder cancer cells." (PMID 34760016, 2021). "HEIH was upregulated in bladder cancer cells compared with normal bladder epithelial cells." (PMID 34760016, 2021). "Therefore, sinomenine was confirmed to suppress the progression of bladder cancer by inhibiting HEIH expression." (PMID 34760016, 2021). "The mRNA expression of HEIH in bladder cancer cells was measured by RT-qPCR." (PMID 34760016, 2021). "Besides this, our findings indicated that sinomenine possesses antitumor effects by suppressing HEIH expression in bladder cancer." (PMID 34760016, 2021). "Taken together, HEIH was observed to be an oncogene in bladder cancer cells." (PMID 34760016, 2021). "Additionally, HEIH knockdown was confirmed to block cell growth and motility, but evoke cell apoptosis in bladder cancer cells." (PMID 34760016, 2021). "Next, the expression of HEIH in bladder cancer cells stimulated with sinomenine was investigated." (PMID 34760016, 2021).
colon cancer (1 paper, 2022). "We identified the pathogenic roles of YBX3 and its regulatory lncRNA HEIH in various cancers and investigated their effects on tumor progression in colon cancer." (PMID 36059530, 2022). "Unexpectedly, our research found that the lncRNA HEIH, which has been reported several times to be highly expressed in multiple tumors, showed the opposite trend in colon cancer (serving as a tumor suppressor gene)." (PMID 36059530, 2022). "We performed a qPCR analysis of cDNA samples from 12 patients from our hospital with distinct stages of colon cancer, and we found that, as the tumor stage progressed, HEIH expression decreased, while YBX3 expression rose." (PMID 36059530, 2022). "Conversely, it was interesting to note that the HEIH expression level was higher in paracancerous tissue of colon cancer patients than in the corresponding cancer tissue and was also higher in patients with higher nodal stage (≥1) and/or metastasis." (PMID 36059530, 2022). "Hence, in this study, we explored the effect of the RBP YBX3 on various genes involved in multiple hallmarks of cancer and the effect of its upstream lncRNA HEIH on oncogenesis and progression across cancers, particularly their role in colon cancer." (PMID 36059530, 2022). "Furthermore, its expression in colon cancer is clinically significant, and there is an obvious negative regulatory association between HEIH and YBX3." (PMID 36059530, 2022). "Among various cancers, especially colon cancer, YBX3 is more related than HEIH expression to the clinical features and prognosis of subgroups." (PMID 36059530, 2022). "Both YBX3 and lncRNA HEIH regulate the therapeutic response through certain common molecular mechanisms, but the role of the tumor regulation system composed of lncRNA-HEIH/YBX3 in the tumor microenvironment (TME) of diverse tumors, especially in colon cancer, has not been fully investigated." (PMID 36059530, 2022).
coronary artery disease (1 paper, 2021). "We aimed to investigate the expression of long noncoding RNA- (lncRNA-) HEIH in patients with coronary artery disease (CAD) and its impact on patients' prognosis." (PMID 35003390, 2021).
retinoblastoma (1 paper, 2021). A malignant tumor that originates in the nuclear layer of the retina. "Consistent with our results, Gao's study has shown that HEIH was overexpressed in retinoblastoma, and HEIH knockdown remarkably suppressed the viability, migration, and invasion of retinoblastoma cells." (PMID 34760016, 2021).
tumor (20 papers, 2014 to 2025). "This study reveals the novel role of tumor-derived exosomal lncRNA HEIH in regulating macrophages via the miR-98-5p/STAT3 axis, advancing understanding of TME-immune cell interactions in HCC therapy." (PMID 40352941, 2025). "This provides evidence for the novel regulatory role of tumor-derived exosomal lncRNA HEIH targeting the miR-98-5p/STAT3 axis in macrophages, aiding the understanding of the complex interactions between the TME and immune cells in HCC treatment." (PMID 40352941, 2025). "HEIH is highly expressed in several tumor types; can promote tumor cell proliferation, migration, invasion, and drug resistance; and is related to a poor prognosis." (PMID 36330457, 2022). "In fact, HEIH reduces miR-939-5p expression, which is associated with the upregulation of NOS2-dependent NO generation and tumor promotion in TNBC (Figure 3B1)." (PMID 34200849, 2021). "The HEIH gene is knocked out, which inhibits cell proliferation and tumor growth." (PMID 36031658, 2022). "A high level of HEIH has been found significantly associated with HBV-related HCC recurrence (HR = 2.1; 95% CI: 1.2–3.7), while another study found HCC patients with lower levels of GAS5 in tumor tissue had a worse overall survival than patients with higher expression (HR = 2.4; 95% CI: 1.6–4.1)." (PMID 26378581, 2015). "Another study reveals the role of the EZH2-related lncRNA HEIH, which is abnormally upregulated in HCC and correlates with poor prognosis in tumor tissues and cell lines." (PMID 40352941, 2025). "Among lncRNA, HEIH and UCA1 develop their oncogenic functions by inhibiting their target miRNAs and consequently reversing the inhibition of NOS and promoting tumor proliferation." (PMID 34200849, 2021). "In this sense, HEIH and UCA1 develop their oncogenic functions by inhibiting their target miRNAs, and consequently reversing the inhibition of NOS and promoting tumor proliferation." (PMID 34200849, 2021). "Moreover, by studying the significance of HEIH and YBX3 on the prognosis of digestive system tumors, we found that they had completely opposite prognostic relationships with the same tumor types, suggesting that there is a suppressive effect between HEIH and YBX3." (PMID 36059530, 2022).
cancer (10 papers, 2015 to 2024). A tumor composed of atypical neoplastic, often pleomorphic cells that invade other tissues. "When we evaluated the diagnostic values of HEIH/YBX3 across cancers among TCGA samples, we found that HEIH played a significant diagnostic role in eight of the 10 cancer types where YBX3 played a significant diagnostic role (AUC > 0.8)." (PMID 36059530, 2022). "Among these potential lncRNAs, AC046143.1 and HEIH have been previously proved to be associated with cancer." (PMID 36118855, 2022). "The cancer-specific roles of these mRNAs suggest the potential importance of HEIH and LINC-PINT in EOC." (PMID 31098301, 2019). "Our findings suggest that the oncogenic system of HEIH/YBX3 could together serve as a biomarker for cancer detection, prognosis, therapy design, and follow-up." (PMID 36059530, 2022). "HEIH has been reported to act as ceRNAs of miRNAs in several human cancers." (PMID 32449803, 2020). "A total of 15,776 samples across 33 cancer types in TCGA and the GTEx database were analyzed for YBX3 and HEIH expression." (PMID 36059530, 2022). "We selected 74 and 5 target mRNAs for HEIH and LINC-PINT, respectively, among which were those involved in important roles in cancer progression." (PMID 31098301, 2019). "Hence, to our knowledge, no existing studies have fully described the significance of HEIH and YBX3 across cancers." (PMID 36059530, 2022).
HEIH also shares sentences with these, for which no sentence is quoted: cholangiocarcinoma (3 papers); breast carcinoma (2); Cirrhosis (2); esophageal cancer (2); non-small cell lung carcinoma (2); chronic hepatitis C (1); colon adenocarcinoma (1); digestive system tumors (1); dyslipidemia (1); esophageal squamous cell carcinoma (1); gastric adenocarcinoma (1); Hepatitis (1); hepatitis B (1); Hypertension (1); nasopharyngeal carcinoma (1); oesophageal cancer (1).